MMP8 (matrix metallopeptidase 8)
Diseases named in the same sentence as MMP8 in open-access papers (continued):
Sharing a sentence is not in itself a finding about the gene and the disease.
infection (65 papers, 2010 to 2025). The state of being infected such as from the introduction of a foreign agent such as serum, vaccine, antigenic substance or organism. "This population includes several neutrophil-associated genes (OLFM4, CD177, SERPINB1, S100P, PTX3 and MMP8), suggesting that there is an accumulation of neutrophils in PBCMs during the course of infection." (PMID 27595844, 2016). "The genes that were suggestive for association with PTB in fetal (IL1A, IL4 and MMP8) and maternal samples (IL-1R2 and IL-6R) in both the MoBa and Cenn studies were mainly infection and inflammation genes (sector D)." (PMID 20140262, 2010). "Moreover, different comorbidities, such as age, genetic susceptibility, and sources of infection, can complicate the level of MMP-8 expression." (PMID 37464428, 2023). "We first examined whether infection was related with release of MMP-8, which represents an important neutrophil-associated collagenase." (PMID 35463648, 2022). "The expression of Mmp8, S100a8 and S100a9 in the mNeu and immNeu of infection groups was predominantly decreased in the blood." (PMID 40874427, 2025). "Using synovial fluid samples, it has been reported that the level of MMP-8 was significantly higher in the patients with post-infectious Lyme arthritis than patients with active infection." (PMID 40392222, 2025). "The test detects two recognized markers of infection, Matrix MetalloProteinase-8 (MMP-8) and Interleukin-6 (IL-6), in a lateral flow assay using peritoneal dialysate taken from the dialysis effluent." (PMID 38893639, 2024). "Infection with DV1-5P7Sp or DV3P4Bm increased MMP-8 mRNA (7.2 × 103 or 1.3 × 104-fold) in the liver (6.5 × 102 or 3.0 × 102-fold) and small intestine." (PMID 38550855, 2024). "By quantitative RT-PCR (qRT-PCR), we confirmed that IL-6, IL-1β, and MMP-8 mRNAs were commonly upregulated in the liver and small intestine after infection and were all suppressed by anti-TNF-α Ab treatment." (PMID 37939119, 2023). "The activity of MMP-8 would increase in many pathophysiological conditions such as severe infection." (PMID 36639750, 2023). "Given that critically ill patients requiring mechanical ventilation often exhibit a high incidence of hypoxia and infection, the elevated levels of MMP-8 observed in this cohort can likely be attributed to these common medical conditions." (PMID 37464428, 2023). "Conversely, control mice exhibit greater expression of Ccl5, Mmp8, Sfrp2, Tmem119, and Tnn after 14 days of infection." (PMID 37845223, 2023). "At the effector level, infection induced massive neutrophil infiltration into the lamina propria of the small intestine and produced neutrophil-derived MMP-8." (PMID 37939119, 2023). "In vivo, STm infections results in transcriptional upregulation of MMPs family genes, Mmp3, Mmp8, and Mmp28 in PPs and mesenteric lymph nodes (mLNs) 2 days post-infection and further Mmp genes in the inflamed caecum up to 3 weeks post infection." (PMID 35733975, 2022). "PA-induced nuclear accumulation of NF-κB, MMP-8 activation, and subsequent occludin degradation were blocked by caAMPKα infection." (PMID 35915511, 2022). "We observed a strong connection of deep infection foci to higher MMP-8 and TIMP-1 levels throughout the 90 days observation period." (PMID 34043679, 2021). "T cells from CD4+ and CD8+ lineages are essential to control bradyzoites containing cysts at the brain, T cells expressing MMP-10 are present at the brain after 21 days of infection, while T cells expressing MMP-8 are observed at 28th day of infection." (PMID 28955329, 2017). "The mRNA levels of MMP-3, MMP-8, MMP-9, and TIMP-1 were analyzed 12 h after FT explant infection with Ngo strain P9, variant 17 (Pil+Opa+)." (PMID 28932707, 2017). "In this study, we show that neutrophils secrete the collagenase MMP-8 in response to direct infection with Mycobacterium tuberculosis and via cellular networks." (PMID 25996154, 2015).
infection (continued). "Bronchial colonisation/infection with Treponema denticola and smoking are independently associated with elevated MMPs (MMP9/MMP12 and MMP8/MMP9, respectively) in the bronchial fluid." (PMID 26656474, 2015). "Such ependymal disruption correlates with infection-induced increases in MMP8, 3, 12, 2, 9 and 16 in addition to dislocated/rearranged patterns of ependymal junction proteins including occludin, cadherin, catenin α and β." (PMID 22731103, 2012). "Matrix metalloprotease 8 (MMP8) is a collagenase with pro-inflammatory effects in infection." (PMID 40655143, 2025). "Similarly, infection with DENV-3 P12/08 increased MMP-8 levels, which were suppressed by anti-TNF-α Ab treatment." (PMID 37939119, 2023). "Indeed, during infection, high levels of MMP-8 and MMP-9 are present in extracellular spleen homogenates and plasma." (PMID 37669943, 2023). "After 14 days of infection, there were 257 genes with greater expression in nociceptor-ablated mice (e.g., Vegfa, IL1a, IL1b, and Tnf) compared to 219 genes with greater expression in control mice (e.g., Alox5, Car2, Ccl5, Elane, and Mmp8)." (PMID 37845223, 2023). "Anti-TNF-α or anti-IL-17A Ab treatment suppressed the infection-induced upregulation of MMP-8." (PMID 37939119, 2023). "However, increased MMP-8 presence during infection is the result of both, with the major N3 subpopulation showing the highest level of expression and the N4 mature neutrophils showing increased infection-induced expression as well as a cell number expansion." (PMID 37669943, 2023). "Taken together, these findings suggest that MAC induce NET formation, IL-8 release and NETs-dependent release of MMP-8 and -9 from neutrophils, leading to neutrophil accumulation and further inflammation, thereby enhancing the progression of infection in the lungs." (PMID 35410994, 2022). "Consequently, we uncovered distinct TJ disturbances of claudins, associated with upregulation of MMP-8 and MMP-13 expression in infected CP in vivo, which was confirmed by in vitro infection of primary CP epithelial cells." (PMID 35027063, 2022). "Infection leading to imbalance of MMP-8 and TIMP-1 may be related to initiation of preterm delivery." (PMID 28167848, 2017). "We demonstrate that AMPK regulates MMP-8 dependent tissue destruction, both at the level of protein secretion and gene expression, using data from a cellular model of infection and by investigating biopsy samples from TB patients and immune responses in AMPK deficient patients." (PMID 25996154, 2015). "In addition to the effect of MMP-8 on tight junction components, adherence of the cell to the basement membrane was also affected in our infection model system." (PMID 20442866, 2010). "In addition to the effect of MMP-8 on the tight junction component, MMP-8 activity also accounted for brain endothelial cell detachment that occurred during prolonged time of infection with N. meningitidis." (PMID 20442866, 2010). "Since MMP-8 resulted in cleavage of occludin we next analyzed whether infection of HBMEC triggers release of active MMPs." (PMID 20442866, 2010). "The cleavage of occludin mediated by MMP-8 in the first extracellular loop suggested that the C-terminal part of occludin is not affected during infection and therefore remains associated with the membrane and still interacts with ZO-1." (PMID 20442866, 2010). "Importantly, compared to WT-infected brains, the K101R infection resulted in significantly higher expression levels of genes involved in the regulation of cytokine production and inflammatory response, including Chil3, Arg1, and Mmp8." (PMID 37884553, 2023). "The clinical significance of this finding might be that increased MMP-8 in the CMP indicates an increased risk of intrauterine infection, whereas significantly elevated levels in the amniotic fluid indicate the presence of an actual infection." (PMID 20868473, 2010).
infection (continued). "Thus, exposure to environmental tobacco smoke may be a relevant modulator of infection rates by periodontopathogens like Treponema denticola and Porphyromonas gingivalis, whose action on IL-8 and salivary MMP-8 could distinguish clinical findings in both passive and active smokers." (PMID 40429544, 2025). "MMP8 and MMP9 were upregulated in the mouse brain infected with CVS-B2c at 6 days post-infection which helped in enhancing blood-brain barrier (BBB) permeability." (PMID 37692167, 2023). "In conclusion, the present study is the first to demonstrate a connection of plasma MMP-8 and MMP-8/TIMP-1 to disease severity, presence of a deep infection focus and mortality in MS-SAB patients." (PMID 34043679, 2021). "The research results obtained by the author indicate that the concentrations of MMP-8, MMP-9 (and others) were higher in the case of suspected infection compared to the control group and also in the case of intrauterine infection." (PMID 34501333, 2021). "The changes in the other four genes were more complex, but also depended on the time points: At day 3 post infection, Balb/c mice produced more MMP-13 and less MMP-8, MMP-9, and TIMP-1, but this trend was reversed at three later time points." (PMID 22665968, 2012). "It is therefore highly probable that the inflammatory process, as reflected by the elevated concentrations of MMP-8, MMP-9 and IL-8 in the CMP-dists, protects the uterine cavity against ascending infection." (PMID 20868473, 2010). "Thus, an imbalance between the circulating levels of specific MMPs and TIMPs—especially increased MMP-1 and MMP-8 to TIMP-4 and decreased MMP-1 and MMP-7 to TIMP-1 and 2—is characteristic of filarial lymphedema in the presence of active infection." (PMID 22679524, 2012). "Specifically, MMP9, MMP8, and MMP14-proteolysis of IL-8, which is also upregulated in LGMDD2 patients, may lead to an increase in its chemotactic potency by guiding the neutrophils to the site of injury or infection." (PMID 35646913, 2022). "One could hypothesize that in whole CMPs from preterm deliveries, not only the distal but also the proximal part of the CMP, is rich in leukocytes, MMP-8, MMP-9, and IL-8, thereby reflecting an ascending infection that has overcome the antimicrobial properties of the CMP." (PMID 20868473, 2010). "In addition, our data showed the involvement of MMP-8 in morphological (occludin relocation) and functional (permeability increase) alterations, and blocking MMP-8 activity preserved occludin attached at the cell membrane under infection and reduced increase of permeability." (PMID 20442866, 2010). "Furthermore, the only very preterm CMP included in the study displayed very high concentrations of MMP-8 and MMP-9 even though neither the mother nor the newborn showed signs of an infection." (PMID 20868473, 2010).
cardiovascular diseases (15 papers, 2011 to 2025). "Elevated plasma and serum levels of MMP-8 associate with conditions such as peritonitis, rheumatoid arthritis and cardiovascular diseases." (PMID 33363547, 2020). "Several studies have been reported that MMP-7 and MMP-8 increased the risk of incident cardiovascular disease events." (PMID 31752174, 2019). "Unfortunately, both serum and plasma MMP-8 concentrations have only rarely been determined in the context of cardiovascular diseases (CVD), so the possible association between circulating MMP-8 levels and the cardiovascular risk remains to be evaluated." (PMID 23365489, 2013). "Elevated salivary levels of MMP-8 have been linked with an increased risk for cardiovascular disease." (PMID 23637817, 2013). "Moreover, FH V62I polymorphism correlates with the serum levels of matrix metalloproteinase 8 (MMP-8), which is a pro-inflammatory enzyme linked to cardiovascular diseases, thus suggesting an additional AD protective role for FH." (PMID 40637922, 2025). "Local carotid plaque MMP-8 level corresponds with a higher frequency of secondary manifestations of cardiovascular disease during follow-up, and increased plasma levels are predictive for subsequent all-cause mortality." (PMID 32486345, 2020). "Clinical studies have suggested a role for MMP8 in cardiovascular diseases." (PMID 36291087, 2022). "This may be particularly so considering that neutrophils operating via their various granule contents (such as MMP8) have increasingly been recognized to play a prominent role in the etiopathogenesis of various other diseases, including cardiovascular diseases." (PMID 37018379, 2023). "Serum and plasma matrix metalloproteinase-8 (MMP-8) levels have been demonstrated to reflect disease severity and plaque instability in cardiovascular diseases." (PMID 29064046, 2018). "MMP-8 and TIMP-1 levels, as well as the MMP-8/TIMP-1 ratio in serum reflect progression and severity of cardiovascular diseases." (PMID 23637817, 2013). "GCF MMP-8 concentrations were significantly increased in AMI patients as compared to patients without cardiovascular disease with similar periodontal conditions." (PMID 37342498, 2023).
bacterial infection (5 papers, 2008 to 2023). "The downregulated proteins were related to the reduction in markers of inflammation (e.g., Alox5, Lbp, C5, Il36b, and Mmp8) and bacterial infections (e.g., Masp2, Mbl1, Krt34, and Cfd)." (PMID 38030636, 2023). "The role of increased MMP-8 and MMP-9 concentrations and activity in bacterial infection of the lung is, in contrast to chronic disease, under debate." (PMID 18700005, 2008).
infectious disease (5 papers, 2015 to 2025). A disorder directly resulting from the presence and activity of a microbial, viral, or parasitic agent in humans. "Indeed, the potential of MMP8 as a biomarker for severity in infectious diseases is an emerging area of research." (PMID 41452925, 2025). "MMPs, including MMP-2, MMP-3, and MMP-8, are involved in the pathogenesis of infectious diseases." (PMID 36142454, 2022). "We measured the levels of MMP-8, MMP-9 and TIMP-1 by specific immunoassays previously found to be suitable for diagnosis and monitoring of systemic low-grade inflammation associated with cardiovascular and infectious diseases as well as other inflammatory states." (PMID 28407807, 2017). "Neutrophil-derived MMP-8 is increased during pulmonary infection, indicating crucial role of MMP-8 played in the immunopathology of infectious disease." (PMID 37766868, 2023).
inflammation (5 papers, 2014 to 2023). Aberrant reaction of the microcirculation characterized by movement of fluid and leukocytes from the blood into extravascular tissues. "In practice, a rapid IL-6 or a rapid bedside MMP-8 test of amniotic fluid can be used for the rapid diagnosis of intra-amniotic inflammation and nanopore sequencing would allow the diagnosis of the causative microbe or, in the absence of microorganisms, sterile intra-amniotic inflammation." (PMID 36503654, 2023).
heart disease (4 papers, 2013 to 2022). "Other studies have also demonstrated that exogenous H2S sources (NaHS) led to reduction of MMP-13 and/or MMP-8 levels in human chondrocytes under inflammatory conditions and in a model of rat heart disease." (PMID 27362269, 2016). "In our study, participants who responded that they had heart disease did not have elevated concentrations of MMP-8." (PMID 23637817, 2013).
respiratory disease (4 papers, 2012 to 2025). "The mechanisms behind the association of MMP-8 levels with mortality from respiratory disease are likely to involve the tissue destructive effects of this MMP." (PMID 23031278, 2012). "However MMP-8 levels were strongly associated with mortality due to respiratory disease (P < 0.0001, 1.3% hazard ratio increase per ng/ml)." (PMID 23031278, 2012). "However, the association of high MMP-8 levels with patients later dying of respiratory disease remained after such adjustment (P = 0.01)." (PMID 23031278, 2012). "Stratification by causes of death also demonstrated that higher levels of MMP-2 were found in patients who later died from circulatory disease, but higher levels of MMP-8 were found in patients who died from respiratory disease." (PMID 23031278, 2012). "The serum level of MMP-8 is a strong predictor of mortality in RA, especially that due to respiratory disease." (PMID 23031278, 2012). "Our data indicate that the serum level of MMP-8 (neutrophil collagenase) is a strong predictor of mortality in RA, especially that due to respiratory disease." (PMID 23031278, 2012). "Analyses of cause-specific mortality demonstrated significant associations of MMP-8 and MMP-9 with mortality due to respiratory disease." (PMID 23031278, 2012). "Our results indicate that in patients with established RA, high serum levels of MMP-8 are predictive of respiratory disease-related mortality, and provide additional predictive information on mortality in RA, which is not provided by traditional measures." (PMID 23031278, 2012). "Additionally, the MMP-8 : TIMP-1 ratio can identify cases of respiratory disease, in which clinical signs and cytologic findings are almost unremarkable, which is very helpful, when examining horses in remission." (PMID 26770019, 2015). "MMPs, TIMPs, and in particular the MMP-8 : TIMP ratios are useful to evaluate the severity and character of respiratory disease and may have prognostic value for equine pneumopathies." (PMID 26770019, 2015). "Multivariate analysis of mortality due to respiratory disease showed that MMP-8 level was a highly significant predictor along with age, nodular disease and presence of RF." (PMID 23031278, 2012). "Although we and others have shown that higher levels of MMP-8 are associated with smoking in RA and other conditions, our results suggest that the association of MMP-8 with all-cause and respiratory disease mortality is independent of smoking." (PMID 23031278, 2012).
cancers of the gastrointestinal tract (2 papers, 2019 to 2022). "In other cancers of the gastrointestinal tract, the prognostic role of MMP-8 remains controversial." (PMID 35328734, 2022).
kidney disease (2 papers, 2023 to 2025). "Among the remaining proteins, some are associated with chronic inflammation in kidney disease (Chil3 and Mmp8), others are components of the glomerular basement membrane (Col18a1), and others have an uncertain function in kidney disease." (PMID 39911133, 2025).
adenocarcinoma (1 paper, 2021). A common cancer characterized by the presence of malignant glandular cells. "The interaction of MMP8 and other signalling molecules within and adjacent tumoral tissues, including immune cells, are rather elusive, particularly of adenocarcinoma cell type." (PMID 34356991, 2021). "This study examines the in vitro changes in the migration and proliferative potentials of A549 adenocarcinoma cells, along with its apoptotic activity, when the single guide RNA (sgRNA) targeting on MMP8 was delivered by lipofection together with Cas9 protein." (PMID 34356991, 2021). "However, MMP8 protein level did not change in adenocarcinoma histology type when compared with normal tissue regions in the same patients." (PMID 34356991, 2021).
metabolic disorders (1 paper, 2020). "Women's health; Pregnancy; Metabolism; Metabolic disorder; Nutrition; Obstetrics & gynecology; IGFBP-1, Insulin, Lipids, MMP-8." (PMID 32923723, 2020).
neurologic disease (1 paper, 2025). "Also, data on the varicella zoster virus (VZV) neurologic disease in humans suggest involvement of multiple MMPs, with an increased concentration of MMP2 and to a lesser degree of MMP3 and MMP9 both in serum and CSF, as well as of MMP8 and MMP12 in CSF only." (PMID 40003967, 2025).